MRC1 (mannose receptor C-type 1)
Diseases named in the same sentence as MRC1 in open-access papers (continued):
Sharing a sentence is not in itself a finding about the gene and the disease.
COVID-19 (27 papers, 2021 to 2026). A disease caused by infection with severe acute respiratory syndrome coronavirus 2. "MRC1, the target of metformin which has been approved to suppress M2-like polarization of macrophages, was also proposed as potential drug candidate for COVID-19 treatment." (PMID 33859163, 2021). "TSPO and MRC1 were highly expressed in macrophage clusters enriched in healthy controls and moderate COVID-19 patients." (PMID 34239034, 2021). "The univariate Cox analysis highlighted that 7 genes (including MRC1, CP, ITGA5, SNCA, HARS1, ENPP1, and PLAU) were significantly (p < 0.05) associated with CHOL/COVID-19." (PMID 34176789, 2021). "Decreased phagocytosis in severe COVID-19 was evident by the downregulation of MSR1, Neuropilin 1 (NRP1), and MRC1, with more significant decreases in SevereD." (PMID 39928675, 2025). "As per the independent prognostic and survival analyses, few of the important differentially expressed genes, including MRC1, CP, ITGA5, SNCA, HARS1, ENPP1, and PLAU may function as potent biomarkers for screening and characterizing different stages of CHOL patients with COVID-19." (PMID 34176789, 2021).
asthma (26 papers, 2010 to 2026). "Accumulating studies have also revealed that the MRC1 has been associated with increased susceptibility to asthma and pulmonary tuberculosis." (PMID 36157207, 2022). "Single-nucleotide polymorphisms (SNPs) of MRC1 have been associated with asthma in Japanese and African-American populations." (PMID 28835901, 2017). "In fact, variants in MRC1 have been associated with asthma and sarcoidosis." (PMID 33092534, 2020). "We also reported the association of MRC1 gene polymorphism and risk of asthma in two independent ethnically diverse populations, suggesting that MRC1 might be involved in the pathogenesis of a number of chronic inflammatory diseases." (PMID 21029423, 2010). "Girodet and colleagues demonstrated that BALF from asthma patients contains markedly more M2 macrophages than that from healthy controls, with MRC1 and MHC II expression increased by more than threefold." (PMID 41602451, 2026). "Thirdly, although we found that the cytokines or markers, such as IL-33, ST2, IL-4 and MRC1, participated in the treatment of calycosin in asthma, the direct molecular mechanism of action is still unclear." (PMID 38650035, 2024). "M2 macrophages, characterized by their expression of Mrc1, Arg1, and Chil3 are well-qualified candidates as they secrete IL-13, are known to activate T cells and are upregulated in the blood of asthma patients." (PMID 35697721, 2022).
atherosclerosis (21 papers, 2013 to 2025). A disease characterized by the build-up of fatty material and calcium deposition in the arterial wall resulting in partial or complete occlusion of the arterial lumen. "Monocytes and monocyte-derived cells, expressing markers of “alternative activation” such as arginase-1 (Arg1) and mannose receptor (Mrc1, CD206), drive healing processes in animal models of cutaneous wounds, atherosclerosis, and myocardial ischemia." (PMID 37961609, 2023). "M2 macrophages are anti-inflammatory macrophages identified by the expression of molecules such as IL-10, arginase 1 (Arg1), and Mrc1 (also known as CD206) and are involved in tissue repair, enhancing plaque stability during atherosclerosis 114-117." (PMID 31588227, 2019).
endometriosis (20 papers, 2016 to 2025). The growth of functional endometrial tissue in anatomic sites outside the uterine body. "The MRC1 expression on macrophages significantly increased in distinct inflammatory conditions, such as EM, suggesting its significant role in endometriosis development." (PMID 34295919, 2021). "Moreover, overexpression of several genes including Cyp2r1, Fabp4, Mrc1, and Rock2 has been shown in the liver and visceral adipose tissue of endometriosis cases." (PMID 34806344, 2021). "Treatment with control sEVs did not alter these changes, whereas endometriosis sEVs reduced IL1B expression and did not generate significant changes in MRC1." (PMID 39062452, 2024). "Although no changes in cell uptake were detected, sEVs from endometriosis induced a polarization of macrophages toward an M2 phenotype, characterized by lower IL1B and TNF expression and a tendency to increase MRC1 and ARG1 levels." (PMID 39062452, 2024). "However, rosiglitazone did not modify the changes in macrophage phenotype induced by endometriosis sEVs, with no significant changes in IL1B or MRC1 expression being observed." (PMID 39062452, 2024). "qRT-PCR was carried out using the total RNA that was extracted from 10 pairs of normal endometrium and EM tissues and showed higher expressions of BIN2, CCR5, and MRC1 and lower expressions of SYK and ADAM12 in endometriosis tissue than in non-endometriosis tissue." (PMID 34295919, 2021).
myocardial infarction (19 papers, 2015 to 2025). Gross necrosis of the myocardium, as a result of interruption of the blood supply to the area, as in coronary thrombosis. "This evidence collectively supports our findings, suggesting a critical interaction between miR-23a-3p and MRC1 in myocardial infarction." (PMID 39216003, 2024).
metastatic tumors (18 papers, 2014 to 2025). "A previous study observed a dramatic increase in SPP1+ and MRC1+ CCL18+ macrophages in metastatic tumors, which corroborated the potentially suppressive TME in liver metastases." (PMID 37256123, 2023). "The authors found that MRC1 expression in metastatic LNs was higher than that in metastatic tumors, leading them to conclude that a high percentage of C1QA + MRC1 macrophages might be associated with tumor metastasis." (PMID 40612935, 2025). "To further address whether the M2-like components of pTAMs/mTAMs harbored different characteristics, we sorted M2 marker-expressing macrophages (F4/80+Mrc1+) from primary and metastatic tumors." (PMID 30218063, 2018). "We found that myeloid components in human metastatic tumors were mainly composed of monocytes and TAMs, and all three TAM clusters highly expressed lipid-associated TAM markers (APOE, C1QA, and TREM2) and exhibited a pro-tumoral phenotype featured by CD206 (MRC1) expression." (PMID 40394007, 2025). "Also, pro-tumorigenic macrophage marker gene CD206 (Mrc1) and myeloid marker gene CD11b (Itgam) on average was 2.8× and 2.4× higher, respectively, in the metastatic tumors compared to non-metastatic carcinomas." (PMID 31881983, 2019).
breast tumor (17 papers, 2013 to 2025). "In our analysis of the TCGA breast tumor cohort, we observed significant positive correlations between TREM1 expression and the expression of TREM-1 target cytokines (IL1B, IL8, IL6 and CCL2) and markers of MDSCs and TAMs (CD11B/ITGAM, OLR1, CD14 and CD206/MRC1)." (PMID 34956864, 2021).
diabetes (15 papers, 2019 to 2026). "Interestingly, Mrc1 is expressed by both macrophages and medullary sinusoidal endothelial cells, where its expression increases following the onset of diabetes mellitus within a panel of inflammatory genes." (PMID 36557243, 2022). "At 30 days, M2 macrophage markers Cd163, Mrc1 and Msr1 (CD204) were decreased in diabetes-prone animals." (PMID 31601915, 2019).
periodontitis (14 papers, 2020 to 2026). An acute or chronic inflammatory process that affects the tissues that surround and support the teeth. "On the other hand, the expression of the M2 macrophage surface marker, CD206 (Mrc1), was unchanged by periodontitis or liraglutide-treated periodontitis." (PMID 33274238, 2020).
brain tumors (13 papers, 2004 to 2025). "Gene profiling revealed that BV2 cells expressed higher levels of both M2‐associated genes (Maf, Selenop, P2ry14, Mrc1, Ctsc, and Cxcr4) and M1‐associated genes (Il7r, Atf3, and Gadd45g) compared to RAW264.7 cells, suggesting its multifaceted role in interaction with brain tumors." (PMID 40747560, 2025). "At the 6‐h time‐point, immunostaining on brain tumor sections revealed that macrophages in the tumor labeled with MHCII antibody were negative for MRC1." (PMID 29038312, 2017).
ischemia (13 papers, 2015 to 2024). A hypoperfusion of the BLOOD through an organ or tissue caused by a PATHOLOGIC CONSTRICTION or obstruction of its BLOOD VESSELS, or an absence of BLOOD CIRCULATION. "We further verified the features of the Mrc1+ Igf1+ macrophage subset in a unilateral ischemia-reperfusion injury (IRI) model (GSE174324)." (PMID 38389846, 2024).
lymphoma (13 papers, 2016 to 2026). A malignant (clonal) proliferation of B- lymphocytes or T- lymphocytes which involves the lymph nodes, bone marrow and/or extranodal sites. "The present study sheds new light on the molecular interaction between HL cells and TAMs and shows that HL‐educated TAMs are capable of supporting tissue remodeling and lymphoma dissemination involving the mannose receptor 1 (MRC1/CD206)." (PMID 31825135, 2020). "Coculture of M(IFN-γ/LPS) macrophages with apoptotic lymphoma cells significantly increased the expression of Mrc1, Timp2, Cd36, Pparg and Gas6, whereas the expression of Tnf and Il6 were significantly decreased." (PMID 28157210, 2017). "The upregulation of Gas6, Mrc1, Cd36 and Timp2 expression by M(IFN-γ/LPS) macrophages was specific for coculture with apoptotic cells, as coculture with unstimulated or Bcl-2-transfected lymphoma cells did not lead to a significant upregulation of these genes." (PMID 28157210, 2017).
bladder cancer (11 papers, 2001 to 2025). "In addition, SKA3 expression in bladder cancer was significantly correlated with M2 macrophage markers, including MRC1 and CD163, and Th2 cell markers, including CCR3 and IL-4." (PMID 35546682, 2022). "Moreover, SKA3 expression was positively correlated with gene markers of M2 macrophage such as MRC1 and CD163 in bladder cancer." (PMID 35546682, 2022).
Hyperglycemia (11 papers, 2015 to 2025). An increased concentration of glucose in the blood. "Interestingly, we found that hyperglycemia inhibited IL-10-secreting M2-like macrophage polarization, as revealed by decreased Arg1 and Mrc1 gene induction accompanied by a decrease in STAT3 and STAT6 signaling pathway activation." (PMID 29081777, 2017). "It is worth noting that our data reveal a specific hyperglycemia-associated reduction in TEMs rather than a global reduction in the total number of MRC-1+ M2 macrophages." (PMID 25961566, 2015).
viral infection (11 papers, 2014 to 2025). "MRC1 was also found to be down-regulated in the MDMs of immunosuppressed patients and this can also contribute to a less efficient innate host defense mechanism, considering its important role against viral infection." (PMID 41226528, 2025).
fibrosis (10 papers, 2014 to 2025). the formation of excess fibrous connective tissue in an organ or tissue in a reparative or reactive process. "Differentially expressed genes in Mrc1+ cTMs also point to the potential role of Mrc1+GFPlo cTMs in the accumulation of cardiac fibrosis in the aging heart." (PMID 24861132, 2014).
influenza (9 papers, 2012 to 2025). An acute viral infection of the respiratory tract, occurring in isolated cases, in epidemics, or in pandemics; it is caused by serologically different strains of viruses (influenzaviruses) designated A, B, and C, has a 3-day incubation period, and usually lasts for 3 to 10 days. "We have observed abortive replication of influenza in an avian macrophage cell line (KS and CB, Unpublished observations), which would allow a similar protective role for the MRC1L genes to that of MRC1 in the mouse, in generating effective responses." (PMID 25390371, 2014). "Influenza infection significantly decreased mRNA level of macrophage receptors CLEC7A, MSR1, CD36, and MRC1." (PMID 22396727, 2012).
liver cancer (9 papers, 2013 to 2025). An epithelial or non-epithelial malignant neoplasm that arises from the liver. "MRC1, on the other hand, is expressed in liver sinusoidal endothelial cells and liver macrophages and less investigated in liver cancer." (PMID 23724146, 2013).
osteosarcoma (9 papers, 2020 to 2025). A usually aggressive malignant bone-forming mesenchymal neoplasm, predominantly affecting adolescents and young adults. "Firstly, we referred to two data sets, GSE12865 and GSE14395, and showed that there were high expression levels of four classical M2 macrophages markers, CD163, CCR2, and MRC1, in human osteosarcoma tissue samples." (PMID 35889217, 2022). "However, IL1B_TAM and FCN1_TAM cells also positively expressed the M2‐TAM signature genes, including MRC1, CD206, MS4A4A and IL4I1, suggesting that they were undergoing the transition into M2‐TAM in osteosarcoma TME." (PMID 36305631, 2022). "The vascularendothelial cell population in the osteosarcoma lesion tissues exhibiteda PECAM1­(+), CDH5­(+) phenotype, whereas the macrophage populationwas predominantly of the M2 type, expressing CD163­(+) and MRC1­(+),consistent with the characteristics of the tumor immune microenvironment." (PMID 40834268, 2025).
Cirrhosis (8 papers, 2016 to 2025). A chronic disorder of the liver in which liver tissue becomes scarred and is partially replaced by regenerative nodules and fibrotic tissue resulting in loss of liver function. "As for the markers in the M2 group, only MRC1 was elevated in HE samples, especially when compared to cirrhosis samples." (PMID 36424620, 2022).
multiple sclerosis (8 papers, 2014 to 2025). A progressive autoimmune disorder affecting the central nervous system resulting in demyelination. "MRC1+ microglia/macrophages have previously been successfully targeted in vivo in a preclinical model of multiple sclerosis using intracranial administration of mannosylated clodronate liposomes." (PMID 29164051, 2017). "This is similar to other findings that no other MRC1 expression was found in the parenchyma, despite acknowledged BBB damage e.g. in multiple sclerosis; and also in excitotoxic damage, acute inflammation and other chronic neurodegeneration models." (PMID 24528486, 2014).
leprosy (7 papers, 2015 to 2020). Leprosy is a chronic infectious disease affecting primarily the skin and peripheral nervous system. "Unexpectedly, in Vietnamese and Brazilian leprosy patients, MRC1 variants were associated with leprosy per se and MB leprosy, but not PB leprosy." (PMID 30116885, 2018). "Although the results have not been confirmed, the rs692527 and rs34856358 variants of the MRC1 gene were found to be associated with PB leprosy, and the rs3138557 variant of the IFNG gene was associated with MB leprosy." (PMID 26793196, 2015). "A study of Vietnamese families analyzed the G396S polymorphism in exon 7 of the MRC1 gene and suggested that it is a protective factor against leprosy per se and MB leprosy." (PMID 26793196, 2015). "In addition, variants of MRC1 have been associated with susceptibility to leprosy in Vietnamese and Brazilian patients and to pulmonary tuberculosis in Chinese patients." (PMID 33092534, 2020). "Notably, the first associated gene, MRC1, had markers associated with PB leprosy in China, while it was associated with the MB form in Brazil and Vietnam." (PMID 30540075, 2018). "Summary of associations between genes of innate immune response MBL2, VDR, NRAMP1, MRC1, and leprosy." (PMID 26793196, 2015). "Indeed, a strong host genetic contribution to leprosy susceptibility has been well established through the identification of leprosy susceptibility genes by both positional cloning (PARK2, LTA, HLA-C, MRC1) and candidate gene approaches (e.g. TLR1, TNF, CUBN and NEBL)." (PMID 28793313, 2017).
osteoarthritis (7 papers, 2021 to 2025). A noninflammatory degenerative joint disease occurring chiefly in older persons, characterized by degeneration of the articular cartilage, hypertrophy of bone at the margins and changes in the synovial membrane. "In the DRG, MRC1 expression has been used to identify “M2-macrophages,” which resolve osteoarthritis- or chemotherapy-induced pain by producing IL-10 or inflammatory pain by transferring mitochondria to sensory neurons." (PMID 38117255, 2024).
allergic asthma (6 papers, 2015 to 2025). A asthma with a basis in a pathological type I hypersensitivity reaction. "M2a cells activate Th2 cells via IL-4 and IL-13 production mediated by C-C Motif chemokine ligand (CCL) 17 and mannose receptor C-Type 1 (MRC1), leading to the development of allergic asthma." (PMID 35387059, 2021). "Therefore, MRC1 has a protective role in allergic asthma which is mediated by allergen uptake and clearance, and this function may be mediated through miR-511-3p; an intronic miRNA encoded by both mouse and human Mrc1/MRC1 genes." (PMID 32024540, 2020). "In murine allergic asthma, MRC1 knockout mice display a significant reduction in the uptake and clearance of allergens by macrophages, together with exacerbated peri-bronchial inflammation and goblet cell hyperplasia." (PMID 32024540, 2020). "In addition, our observation of an allergic asthma-driven increased expression of MafB in tAMs may be in line with reports that Mafb upregulates the expression of M2 polarization markers such as MRC1 and CD163." (PMID 33050608, 2020).
meningioma (6 papers, 2020 to 2023). A generally slow growing tumor attached to the dura mater. "The results showed that the expression of the M2 phenotype‐related genes MRC1 and CD163 was markedly higher in grade II meningioma." (PMID 36994665, 2023).
mesothelioma (6 papers, 2018 to 2023). A usually malignant and aggressive neoplasm of the mesothelium which is often associated with exposure to asbestos. "We report that the expression of ChemR23 coding gene, CMKLR1, in breast and mesothelioma tumors positively correlates to the expression of TAM markers such as CD14, CD163, MRC1 and HLA-DRA, in agreement with ChemR23 detection restricted to macrophages in tumors from patients." (PMID 37539056, 2023).